CSTA (cystatin A)
Diseases named in the same sentence as CSTA in open-access papers (continued):
Sharing a sentence is not in itself a finding about the gene and the disease.
infection (4 papers, 2012 to 2023). The state of being infected such as from the introduction of a foreign agent such as serum, vaccine, antigenic substance or organism. "Regarding the mono-infection data, we noticed that CstA and CstC are differently modulated during infection either with Mtb or HIV in comparison with M. smegmatis." (PMID 34867965, 2021). "RNA was extracted 48 h post-infection and its cDNA assayed for expression of CSTA, using MYOC as a positive control and 18S as the endogenous calibrator." (PMID 22615763, 2012). "Finally, the gen cstA was downregulated as in the aerobic infection." (PMID 37966212, 2023). "When we compared the mono-infections with Mtb or HIV to the coinfection context, we confirmed that CstA and CstC are uniquely modulated by these pathogens and with statistically significant increased gene expression between those time points." (PMID 34867965, 2021).
CSTA also shares sentences with these, for which no sentence is quoted: peeling skin syndrome (3 papers); acral peeling skin syndrome (2); colorectal cancer (2); glaucoma (2); hepatocellular carcinoma (2); metastatic melanoma (2); adenocarcinoma (1); aging (1); autosomal recessive congenital ichthyosis (1); brain cancer (1); colorectal adenocarcinoma (1); coronary artery disease (1); dyskeratosis congenita (1); ectodermal dysplasia (1); glioma (1); gynecological cancers (1); Hyperkeratosis (1); ichthyosis vulgaris (1); inflammatory disease of the skin (1); joint diseases (1); keratolytic winter erythema (1); kidney cancer (1); leukaemia (1); malignant glioma (1); non-small cell lung carcinoma (1); osteoarthritis (1); osteoporosis (1); pachyonychia congenita (1); Palmoplantar keratoderma (1); peeling skin syndrome 1 (1).
A further 6 diseases each share a sentence with CSTA in 1 paper.